NLRP3 (NLR family pyrin domain containing 3)
Diseases named in the same sentence as NLRP3 in open-access papers (continued):
Sharing a sentence is not in itself a finding about the gene and the disease.
Alzheimer disease (continued). "In addition, NBP reduced the inflammatory response in Alzheimer’s disease by inhibiting microglial NLRP3 inflammasome activation." (PMID 36013423, 2022). "NLRP3 inflammasome plays a role in Alzheimer’s disease (AD) process." (PMID 36382256, 2022). "In Alzheimer’s disease (AD) microglia, it was observed that oxidative stress is crucial in the activation of cathepsin B, a cysteine protease which is believed to play a role in both NLRP3 inflammasome activation and neuronal death." (PMID 35216110, 2022). "Thus, in NLRP3KO knockout mice, when modeling Alzheimer’s disease by Aβ injection, an overlap coefficient of 0.42 ± 0.18 was revealed, compared with that in the NLRP3 KO + PBS group of 0.36 ± 0.1 (p > 0.05, Sidak’s correction)." (PMID 34769018, 2021). "Thus, it can be assumed that deletion of Nlrp3 had a protective role in the development of Alzheimer’s disease or mild cognitive impairment accompanied by insulin resistance due to decreased expression of pIRS-Ser." (PMID 34769018, 2021). "The NLRP3 inflammasome has been identified as a therapeutic target for the treatment of Alzheimer's disease, and there are many pharmaceutical and academic initiatives underway to develop new small-molecule inhibitors of the NLRP3 inflammasome (e.g., MCC950 and NBCs)." (PMID 33597269, 2021). "It was experimentally proven that preventing the development of local insulin resistance by blocking NLRP3 inflammasomes and mediated neuroinflammation should be considered a pathogenetically grounded approach to correcting cognitive disorders in Alzheimer’s disease." (PMID 34769018, 2021). "NRXN2 was reported to modulate NLRP3 in AD brain regions to affect Alzheimer's disease." (PMID 34777568, 2021). "The pathogenesis of Alzheimer’s disease (AD) involves activation of many NLRP3 inflammatory bodies, which may be related to amyloid β peptide and aggregation of misfolded proteins." (PMID 33708103, 2021). "For example, in the pathogenesis of Alzheimer's disease (AD), the NLRP3 inflammasome can not only damage cognition through interleukin-1β (IL-1β), which is the classic inflammatory pathway, but can also reduce Aβ removal efficiency and cause spatial memory impairment." (PMID 34666797, 2021). "In addition, the role of NLRP3 is noted to contribute to the pathology of central nervous system diseases including Alzheimer’s disease and Parkinson’s disease." (PMID 33603747, 2020). "Thus, the NLRP3 inflammasome contributes to the development of several human diseases, including gout, Alzheimer’s disease, enteritis and liver disease." (PMID 32312957, 2020). "The NLRP3 inflammasome is involved in a broad spectrum of disorders including but not limited to autoimmune diseases, type-2 diabetes, and neurological disorders such as Alzheimer’s disease (AD) and Parkinson’s disease (PD)." (PMID 32604771, 2020). "We found that Cl- channel inhibition blocked IL-1β release in a NLRP3-dependent model of peritonitis, and previously reported protective effects of the fenamate NSAIDs in rodent models of Alzheimer’s disease that we attributed to an effect on Cl- channel inhibition." (PMID 33216713, 2020). "NLRP3 inflammasome activation has been suggested a robust link to the onset and progression of a wide range of central nervous system (CNS) diseases, such as Alzheimer’s disease (AD), Parkinson’s disease (PD), anxiety, and MDD." (PMID 32635937, 2020). "The dysfunction of NLRP3 (which encodes NOD-, LRR-, and pyrin domain-containing protein 3) inflammasome activation is implicated in a variety of human diseases, including Alzheimer’s disease (AD), prion diseases, type 2 diabetes, and numerous infectious diseases." (PMID 32824985, 2020). "Besides this central role of NLRP3 in inflammation, recent publications show that the NLRP3 inflammasome is also involved in the physiopathology of several neurological disorders including Alzheimer’s disease, Parkinson’s disease, and multiple sclerosis." (PMID 31892810, 2019).
Alzheimer disease (continued). "The NLRP3 inflammasome-activating DAMPs include metabolic danger signals (i.e., cholesterol crystals, uric acid crystals, saturated fatty acids, and islet amyloid polypeptide) and amyloid-β in Alzheimer's disease." (PMID 31417575, 2019). "A1AT time-dependently hampers neuroinflammation by downregulation of Aβ1–42-mediated NLRP3-inflammasome expression and thus may serve as a pharmaceutical opportunity for the treatment of Alzheimer’s disease." (PMID 30261895, 2018). "Furthermore, The APP/PS1 mice (a mouse model for Alzheimer’s disease) with NLRP3 knockout are protected from spatial memory impairment and have a decreased Aβ plaque burden." (PMID 29665808, 2018). "The NLRP3 inflammasome has been reported to participate in the development of diverse inflammatory diseases, including type 2 diabetes, Alzheimer’s disease, and gout, suggesting that NLRP3 might be a potential target for the treatment of inflammatory diseases." (PMID 28779175, 2017). "NLRP3/caspase-1 axis played a central role in the pathogenesis of Alzheimer's disease." (PMID 26924896, 2016). "The authors also suggest that activation of NLRP3 enhances Alzheimer's disease and may be involved in synaptic dysfunction, cognitive impairment, and the restriction of microglial clearance functions." (PMID 24834051, 2014). "Organelle stress and NLRP3 inflammasome activation have been established as pivotal contributors to inflammatory responses and play a significant role in the pathogenesis of neurodegenerative diseases (NDDs), including Alzheimer’s disease (AD) and Parkinson’s disease (PD)." (PMID 41484627, 2026). "Moreover, the NLRP3 inflammasome is involved in Alzheimer’s disease-related neuroinflammation." (PMID 40305201, 2025). "Additionally, NLRP3 inflammasome inhibitors like Tranilast and Oridonin have demonstrated potential in preclinical studies for alleviating neuroinflammation and cognitive deficits in Alzheimer’s disease (AD) models." (PMID 40427569, 2025). "Furthermore, monocytes isolated and cultured from Alzheimer's disease patients exhibited increased gene expression of NLRP3, along with the cytokines IL-1β and IL-18, indicating heightened peripheral NLRP3-mediated immune responses in Alzheimer's disease progression." (PMID 38317229, 2024). "Given the important role of the NLRP3 inflammasome in inflammatory responses, we also have reason to infer the therapeutic prospects of IAld for other NLRP3-related inflammatory diseases such as Alzheimer’s disease (AD), nonalcoholic fatty liver disease (NAFLD), and multiple sclerosis (MS)." (PMID 39334766, 2024). "However, the abnormal activation of the NLRP3 inflammasome has been implicated in the pathogenesis of autoinflammatory diseases such as cryopyrin-associated autoinflammatory syndromes (CAPS) and common diseases such as Alzheimer’s disease and asthma." (PMID 39201704, 2024). "Dysregulation of NLRP3 signaling can trigger various inflammatory responses in the brain, contributing to the development of neurodegenerative diseases such as ischemic stroke, vascular dementia (VaD), Alzheimer’s disease (AD), Parkinson’s disease (PD), and amyotrophic lateral sclerosis (ALS)." (PMID 39764140, 2024). "Formation of the NLRP3 inflammasome is required for glial cell activation and neuroinflammation, and excess microglial inflammasome activity is indeed attracting attention as a potential mediator of chronic neurodegeneration in disorders such as Alzheimer’s disease." (PMID 38132466, 2023). "It should be noted that NLRP3 inflammasome could modulate microglial polarization in a variety of disorders, including intracerebral hemorrhage, depression, ischemic stroke, white matter injury, as well as Alzheimer’s disease." (PMID 38035075, 2023). "It has been reported that NLRP3 inflammasome activation may play an important role in the pathogenesis of inflammatory bowel disease, stroke, Alzheimer’s disease, and cardiovascular disease." (PMID 36337711, 2022).
Alzheimer disease (continued). "At the same time, progesterone has a clear neuroprotective effect on some age-related diseases such as Alzheimer's disease, its regulation of NLRP3 inflammasome activation may be a potential therapeutic target for inhibiting astrocytic neuroinflammation in Alzheimer's disease." (PMID 35305084, 2022). "Therefore, we here summarize the activation mechanism of the NLRP3 inflammasome and its pathological role in AD by searching for the words “inflammasome” and “Alzheimer’s disease” in databases including Web of Science, PubMed, Google Scholar, Sci-hub, and SciFinder." (PMID 36699095, 2022). "Moreover, NLRP3 inflammasome activation is conducive to the evolution of many other medical conditions, including Parkinson's disease, inflammatory bowel disease, Alzheimer’s disease, Crohn’s disease, and liver disease." (PMID 34721038, 2021). "Apart from infectious diseases, several chronic inflammatory conditions such as Alzheimer’s disease, cryopyrin-associated periodic syndrome (CAPS), gouty arthritis, diabetes mellites, Parkinson’s disease, multiple sclerosis etc. have been linked with the aberrant activation of NLRP3 inflammasome." (PMID 34248643, 2021). "The NLRP3 inflammasome can sense numerous danger signals and contribute to sterile neuroinflammation in multiple neurological diseases, including β-amyloid plaques and tau fibrillary tangles, which trigger the NLRP3 signaling pathway in the brains of rodent models of Alzheimer’s disease." (PMID 34572437, 2021). "Therefore, it has been proposed that this NLRP3 beneficial function in homeostasis could become harmful during the onset of inflammatory and metabolic diseases, such as multiple sclerosis or Alzheimer’s disease." (PMID 33802349, 2021). "NLRP3 inflammasome activation by β-amyloid in microglia is necessary for maturation of IL-1β and subsequent inflammatory events; however, the role of NLRP3 activation in Alzheimer's disease in vivo is still unknown." (PMID 24834051, 2014). "Based on these results, the authors conclude that introducing therapeutic treatments targeting the NLRP3 inflammasome may have a beneficial effect on patients with Alzheimer's disease as NLRP3 activation may contribute to the pathogenesis of Alzheimer's disease in humans." (PMID 24834051, 2014). "NLRP3 inflammasome has been widely studied in the pathogenesis of mild cognitive impairments (MCI) and Alzheimer’s Disease (AD)." (PMID 41507841, 2026). "Ramalin alleviates Alzheimer's disease pathology by selectively inhibiting HDAC6, reducing BACE1 levels, and suppressing neuroinflammation through downregulation of the NLRP3 inflammasome and iNOS." (PMID 41488470, 2026). "The most highly cited reference is “The NLRP3 and NLRP1 inflammasomes are activated in Alzheimer’s disease,” published in Molecular Neurodegeneration with Marina Saresella as the first author." (PMID 40538660, 2025). "In this study, a sporadic Alzheimer’s disease (SAD) mouse model induced by streptozotocin (STZ) injection was utilized and demonstrated that NLRP3-mediated microglial training exacerbates microglial pro-inflammatory responses, while impairing Aβ phagocytosis." (PMID 40427569, 2025). "In the streptozotocin-induced Alzheimer’s disease mouse model, the NLRP3 inflammasome inhibitor MCC950 protects against pathological reactive MG by inhibiting the activation of the NLRP3 inflammasome." (PMID 41256774, 2025). "After confirming the mechanism of inhibition of NLRP3 inflammasome by FXN, we wanted to know if its dual pharmacological activity can improve Alzheimer disease pathology." (PMID 39136022, 2024). "In Alzheimer’s disease, TREML2 knockdown suppresses neuroinflammation by inhibiting NLRP3 inflammasome activation and inducing M2 microglial polarization in primary microglia." (PMID 38745316, 2024). "NLRP3 has been reportedly involved with inflammatory bowel disease (IBD), Alzheimer’s disease, and PND." (PMID 37179548, 2023).
Alzheimer disease (continued). "MCC950 is a well-studied and specific NLRP3 inhibitor, which can alleviate the symptoms of mouse models of NLRP3-dependent disease, including NASH, type 2 diabetes, and Alzheimer’s disease." (PMID 37805545, 2023). "In other words, there is a relationship between the NLRP3 inflammasome, COX-2, and Alzheimer's disease (AD)." (PMID 37638222, 2023). "Both NLRP3 and NLRC4 inflammasomes have been shown to be involved in neurodegenerative diseases, including Alzheimer’s disease, Parkinson’s disease, and multiple sclerosis." (PMID 36669831, 2023). "Studies have shown that multiple inflammasomes including NLRP3, NLRC4, and apoptosis inhibitor of macrophage 1 (AIM1) among others are active in complex human CNS diseases including Alzheimer’s disease (AD), ALS, multiple sclerosis (MS) and stroke." (PMID 37575265, 2023). "IL-33 improved Alzheimer's disease-like pathology modulating IL-1β, IL-6, and NLR family pyrin domain containing 3 (NLRP3) genes in the cortices of APP/PS1 mice and decreasing cognitive impairment." (PMID 35224555, 2022). "Mild cognitive impairment and the early symptoms of Alzheimer’s disease are similar to that of chronic neurotoxicity induced by ACR, suggesting the involvement of NLRP3 inflammasomes." (PMID 35399689, 2022). "Amyloid β (Aβ) and/or ATP activate the NLRP3 inflammasome (N3I) via P2X7R in microglia, which is crucial in neuroinflammation in Alzheimer’s disease (AD)." (PMID 35464490, 2022). "Increasing evidence primarily from animal studies suggests that the NLRP3 signaling pathway may be part of the mechanism by which electroacupuncture can treat various diseases, such as inflammatory bowel disease, stroke, Alzheimer’s disease, ischemic heart disease, and inflammatory pain." (PMID 36337711, 2022). "Administration of OLT1177, an NLRP3 inflammasome inhibitor, rescued cognitive impairment and neuroinflammation in an APP/PS1 mouse model of Alzheimer’s disease." (PMID 33534121, 2021). "NLRP3 inflammasome is involved in many inflammatory and aging diseases, and NLRP3 inhibitor MCC950 has anti-inflammatory and antisenescence effects on some diseases such as Alzheimer's disease." (PMID 34777685, 2021). "In the last years, the attention of the researchers is focused on the role of the NLRP3 inflammasome in several brain diseases, including Alzheimer disease (AD), Parkinson’s disease (PD), amyotrophic lateral sclerosis (ALS), TBI and central nervous system (CNS) infection." (PMID 32867310, 2020). "Recent studies on whether blocking or inhibiting the activation of the NLRP3 inflammasome through a nonsteroidal anti-inflammatory drug (fenamate) may be essential in memory loss protection in a mouse model of Alzheimer's disease have shown encouraging results." (PMID 32322412, 2020). "The NLRP3 inflammasome, which is related to kidney diseases, cardiovascular diseases, human immunodeficiency virus (HIV) infection, and Alzheimer's disease, is the most studied type." (PMID 33456483, 2020). "In addition, there is emerging evidence for the participation of the NLRP3 inflammasome as a sensor of metabolic stress (i.e., De Nardo and Latz, 2011), demyelination, and it is also involved in some neurodegenerative disorders such as the multiple sclerosis model and Alzheimer’s disease." (PMID 25136295, 2014). "Other highly cited articles predominantly discuss the role of neuroinflammation in various neurocognitive disorders, including Alzheimer’s disease, addressing immune activation, neuroinflammatory mechanisms, TREM2, NLRP3, cognitive impairment, and their relationship with disease progression." (PMID 40791247, 2025). "The activation of NLRP3 inflammasome by mtDNA has been proposed but not demonstrated in microglia and neurons of a rat model of cerebral I/R, PD, and Alzheimer’s disease (AD)." (PMID 40264103, 2025).
Alzheimer disease (continued). "In Alzheimer’s disease, accumulation of fibrillar peptide amyloid-β after phagocytosis releases cathepsin B that is sensed by NLRP3 (and at a lesser extent NLRP1) and induces activation of NLRP1 and 3 inflammasomes, which in turn have been found to worsen Alzheimer’s disease patient conditions." (PMID 38644450, 2024). "It was reported that NLRP3 inflammasome consisted of three protein subunits, NLRP3, ASC and caspase-1, the activity of NLRP3 inflammasome has been considered as one of the important factors in a variety of CNS diseases, such as Alzheimer’s disease and stroke." (PMID 38570868, 2024). "Some abnormal protein aggregation associated with neurodegenerative diseases, such as amyloid beta peptide (Aβ) in Alzheimer’s disease, α-synuclein in Parkinson’s disease, and SOD1 and TDP-43 in ALS, are known to induce the activity of the NLRP3 inflammasome in a mouse model." (PMID 37891975, 2023). "In Alzheimer’s disease, the characteristic accumulation of β-amyloid peptide may induce neuroinflammation through P2X7 receptor mobilization and subsequent activation of NLRP3/caspase-1 pathway." (PMID 37114062, 2023). "Activation of the NOD-like receptor (NLR) family pyrin domain containing 3 (NLRP3) inflammasome is observed under diverse physiological and pathological conditions, such as caloric restriction, type 2 diabetes, preeclampsia, Alzheimer’s disease and cancer." (PMID 37794178, 2023). "The NLRP3, BACE1, AChE, and GSK-3β are closely related to Alzheimer’s disease." (PMID 35991454, 2022). "A study was carried out in the control group with sham surgery (WT + PBS), in simulating Alzheimer’s disease in wild-type animals (WT + Aβ), in NLRP3 knockout animals with sham surgery (NLRP3 KO + PBS) and in NLRP3 knockout mice with the introduction of beta amyloid (NLRP3 KO + Aβ)." (PMID 34769018, 2021). "These fenamate derivates affect NLRP3-dependent IL-1β secretion in an Alzheimer’s disease in vivo model, without affecting NLRC4 and AIM2 inflammasomes." (PMID 33803783, 2021). "MaR1 promoted inflammation resolution by inhibiting chemotaxis, TNFα, IL1β, IL18 levels and NLRP3 inflammasome or NF-kB activation and regulating microglia activation in rodent models of Alzheimer’s disease, non-compressive lumbar disc herniation or inflammatory pain." (PMID 36670960, 2022). "Therefore, it is likely that the NLRP3 inflammasome plays a key role in type II diabetes, Alzheimer's disease, and other noninfectious inflammatory diseases." (PMID 30105072, 2018). "Studies in mouse models of Alzheimer’s disease, brain injury, myocardial infarction and inflammatory bowel disease could demonstrate a reduction in expression levels of interleukin-1 beta, interleukin-6, MCP-1 and NLRP3 upon treatment with pterostilbene and prebiotics." (PMID 36906614, 2023).